LTA4H (leukotriene A4 hydrolase)
Diseases named in the same sentence as LTA4H in open-access papers (continued):
Sharing a sentence is not in itself a finding about the gene and the disease.
cancer (13 papers, 2011 to 2025). A tumor composed of atypical neoplastic, often pleomorphic cells that invade other tissues. "Importantly, GO results revealed that LTA4H-bound proteins were considerably overrepresented in pathways associated with cancer, including mitotic cell cycle, DNA repair, RNA splicing related pathways and RNA metabolism pathways." (PMID 36923505, 2023). "Our findings provide actionable targets (CACNA1C, CALM1, ACE, and LTA4H) for drug repurposing trials and underscore the clinical importance of personalized antihypertensive therapy in cancer prevention." (PMID 40535814, 2025). "There is increasing evidence that LTA4H is overexpressed in many malignant cancers, which promotes cancer cell proliferation." (PMID 36923505, 2023). "And we have identified some crucial LTA4H-bound genes that regulate cancer development, like NEAT1, LINC00657, LTBP3 and ROR2." (PMID 36923505, 2023). "In summary, this is the first time we found that LTA4H preferentially binds to the mRNAs and IncRNAs of cancer-related functional pathway genes in tumor cells by iRIP-Seq experiments and shows enriched binding in specific intron and CDS regions of these genes." (PMID 36923505, 2023). "LTA4H is overexpressed in several cancers including CRC, and several studies have shown that its hydrolase function is implicated in cancer development." (PMID 38304289, 2023). "LTA4H is being investigated as a new target for cancer treatment due to its role in inflammatory response and tumor progression." (PMID 36923505, 2023). "The RNA-binding metabolic enzyme LTA4H is a novel target for cancer chemoprevention and chemotherapy." (PMID 36923505, 2023). "The results across the cancer-promoting gene LINC00657 show there are many LTA4H-bound peaks in IP compared with input." (PMID 36923505, 2023). "LTA4H is overexpressed in several cancers including colorectal, lung and esophageal, skin squamous cell carcinoma, and oral squamous cell carcinoma, and several studies have shown that its hydrolase function is implicated in cancer development." (PMID 35056904, 2021). "LTA4H is highly expressed in certain types of human cancers such as lung cancer, thyroid cancer, and skin cancer." (PMID 32580506, 2020). "Compounds capable of limiting the formation of LTB4, through selective inhibition of LTA4H, are expected to provide potent anti-inflammatory and anti-cancer agents." (PMID 32580506, 2020). "We hypothesized that LTA4H might interact with the RNAs of cancer-related critical genes at the transcriptional or post-transcriptional levels to control the expression of those genes." (PMID 36923505, 2023). "PFK-2/FBPase-2, ATIC, LTA4H and Jmjd6 are four multifunctional enzymes with a proven relevant role in the proliferation and/or survival of cancer cells, and their inhibition can increase the life expectancy of some cancer patients." (PMID 35056904, 2021). "Thus, we speculate that LTA4H not only participates in the regulation of cancer through the inflammatory mediator pathway, but also controls the expression of cancer key genes by interacting with mRNA at the transcriptional or post-transcriptional level." (PMID 36923505, 2023). "Although there are studies reporting the identification of potential inhibitors targeting each of the four described enzymes, to date only LTA4H and PFK-2/FBPase-2 have inhibitors in active clinical development, and only the PFK-2/FBPase-2 inhibitor (PFK158) is being tested in cancer patients." (PMID 35056904, 2021). "During this time, several inhibitors of LTA4H have been proposed, and five of those molecules have reached the early clinical development stage, although none of the clinical trials has targeted cancer patients." (PMID 35056904, 2021). "Therefore, inhibition of LTA4H/LTB4 pathway should serve as a therapeutic approach in pathological processes, such as inflammation and cancer." (PMID 32580506, 2020).
infection (13 papers, 2010 to 2024). The state of being infected such as from the introduction of a foreign agent such as serum, vaccine, antigenic substance or organism. "They subsequently genetically mapped the specific host genes that were responsible for the changes in infection susceptibility and found that the enzyme leukotriene A4 hydrolase (LTA4H) is critical in controlling mycobacterial infection." (PMID 38684467, 2024). "The authors identified a critical role for the enzyme Leukotriene A4 Hydrolase (LTA4H) in determining susceptibility of zebrafish to infection." (PMID 29875747, 2018). "Neutrophil-specific expression of lta4h was sufficient to rescue macrophage aggregation in Lta4h-deficient larvae and increased host survival following infection." (PMID 28658259, 2017). "Recent reports demonstrated that LTA4H deficient mice show a stronger degree of neutrophilic lung inflammation after infection with influenza A X31, Haemophilus influenzae b (Hib) or streptococcus pneumoniae than their wild type counterparts." (PMID 29051536, 2017). "Previous work has shown that overexpression of leukotriene A4 hydrolase (lta4h) generates inflammation due to induction of tumor necrosis factor alpha (tnf-a), making zebrafish more susceptible to infection by Mycobacterium marinum." (PMID 28650995, 2017). "The Tg(lyz:lta4h-2a-mCherry) larvae had significantly increased survival after infection compared to WT larvae during Lta4h depletion (magenta dotted versus black dotted line)." (PMID 28658259, 2017). "Leukotriene A4 hydrolase (LTA4H) is elevated in TB and has been implicated in the spatial organization of lipid signaling within TB lung granulomas by a proteomics approach, and regulates susceptibility to infection." (PMID 38512356, 2024). "Furthermore, conventional intracellular epoxide hydrolase activity of LTA4H was augmented by infection and the neutrophil chemoattractant LTB4 was released into the BALF." (PMID 26400771, 2015). "The effect of M marinum after IP and mucosal infection showed common overrepresented (e.g., ribosomal proteins, lysine-tRNA ligase, and leukotriene A4 hydrolase LTA4H) and underrepresented (e.g., complement components including C3, annexin, and tropomyosin alpha-1) proteins in response to infection." (PMID 32344637, 2020). "The murine model of Hib infection was chosen to dissect the dual activities of LTA4H, as it represents a non-complicated infection whereby the pathogen is readily cleared but elicits a robust pulmonary neutrophilia that is rapidly resolved." (PMID 26400771, 2015). "To investigate the dual roles of LTA4H, we have primarily utilized an acute lung injury model of Hib infection—a model chosen since it evokes a robust pulmonary neutrophilia, but both inflammation and infection are readily resolved without complication." (PMID 26400771, 2015).
tumor (13 papers, 2011 to 2025). "Inhibition of LTA4H is associated with chronic inflammation, and mutations in this gene may reflect de-differentiation of the tumor, although the recurrent nature of the mutations rather suggests a gain-of-function mutation." (PMID 26377837, 2015). "Therefore, our discoveries could shed light on the underlying mechanism of LTA4H in promoting tumor development and provide a new potential anti-tumor target." (PMID 36923505, 2023). "Future studies could evaluate the CSTB, PGK1, LTA4H levels in saliva according to recurrence and/or second primary tumor, which were relevant clinical data associated with their expression in the tissues and are also clinical challenges for therapeutic management in OSCC." (PMID 30185791, 2018). "More notably, LTA4H-binding genes were significantly enriched in the mitotic cell cycle, DNA repair, RNA splicing-related pathways, and RNA metabolism pathways, which means that LTA4H has tumor-related alternative splicing regulatory functions." (PMID 36923505, 2023). "In summary, we hypothesized that LTA4H is preferentially bound to genes related to tumor formation and progression." (PMID 36923505, 2023). "LTA4H/LTA4H expression is elevated in 4 out of 31 analyzed tumor types." (PMID 36765904, 2023). "The majority of proteins (ACTR2, CSTB, LTA4H, PGK1, NDRG1, FSCN1, ITGAV, THBS2) significantly associated with clinical parameters showed lower expression in the ITF of the tumor stroma or neoplastic islands, with the exception of COL6A1, COL1A2, S100A8, S110A9, and MB." (PMID 30185791, 2018). "However, to understand the specific mechanism of LTA4H in tumor cells, more study is necessary." (PMID 36923505, 2023). "Overall, the results of this study indicate that LTA4H and FXR1 are extensively expressed in canine oral melanomas and suggest that they can play a role in tumor oncogenesis process." (PMID 34966807, 2021). "Although LTA4H and FXR1 seem unrelated to tumor behavior, their extensive expression in the present cohort of cases suggest that they may play a role in canine oral melanoma oncogenesis." (PMID 34966807, 2021). "Among them, 13 proteins correlated with clinicopathological parameters and of these proteins, eight proteins were identified in neoplastic islands (ACTR2, CSTB, COL1A2, LTA4H, PGK1, NDRG1, S100A8, S100A9) and five proteins were identified in tumor stroma (COL6A1, FSCN1, ITGAV, MB, THBS2)." (PMID 30185791, 2018). "However, with this significant increase in the size cohort, LTA4H, PGK1, and ITGAV staining were identified with a slight variation within the lower and higher scores in each region, either ITF or inner tumor." (PMID 30185791, 2018). "In addition, in the IHC analysis of neoplastic island proteins, LTA4H and PGK1 showed peripheral staining in neoplastic cells and were also detected in cells in the tumor stroma, such as inflammatory cells." (PMID 30185791, 2018). "Cystatin-B (CSTB), leukotriene A-4 hydrolase (LTA4H), protein NDRG1 (NDRG1), and phosphoglycerate kinase 1 (PGK1) from the neoplastic island dataset and collagen alpha-1(VI) chain (COL6A1), integrin alpha-V (ITGAV) and myoglobin (MB) from the tumor stromal dataset were prioritized." (PMID 30185791, 2018).
inflammation (2 papers, 2015 to 2022). Aberrant reaction of the microcirculation characterized by movement of fluid and leukocytes from the blood into extravascular tissues. "Loss of LTA4H function clearly resulted in an exacerbated PGP-driven pulmonary inflammation and illness in response to Hib infection." (PMID 26400771, 2015).
neurodegenerative disease (1 paper, 2025). A disorder of the central nervous system characterized by gradual and progressive loss of neural tissue and neurologic function. "Several ALS-increased DEGs had previously been recognized as markers for microglia phenotypes detected in other neurodegenerative diseases (e.g., GPNMB, APOE, LTA4H)." (PMID 40700130, 2025).
LTA4H also shares sentences with these, for which no sentence is quoted: meningitis (3 papers); inflammatory bowel disease (2); peritonitis (2); acne inversa (1); acute coronary syndrome (1); allergic dermatitis (1); breast tumor (1); cardiovascular disease (1); colitis (1); colon adenocarcinoma (1); colorectal adenoma (1); Crohn disease (1); cystic fibrosis (1); Dengue virus infection (1); eczema (1); esophageal adenocarcinoma (1); head and neck squamous cell carcinoma (1); hepatocellular carcinoma (1); hyperprolactinemia (1); infarction (1); intestinal tuberculosis (1); ischemia (1); leukoaraiosis (1); lymphoma (1); metabolic disorders (1); pulmonary fibrosis (1); pulmonary hypertension (1); renal carcinoma (1); thyroid cancer (1).